CHGB (chromogranin B)
Description:
Secretogranin-1 is a neuroendocrine secretory granule protein, which may be the precursor for other biologically active peptides.
Synonyms: SgI; SCG1
Tractability: Antibody: UniProt places it where antibodies can reach, with high confidence; UniProt predicts a signal peptide or a membrane-spanning region; its Gene Ontology location is reachable by antibodies, with medium confidence. PROTAC: its protein half-life has been measured.
Gene: Protein-coding gene on chromosome 20 (5,911,394 to 5,925,361, forward strand). Ensembl gene ENSG00000089199.
Subcellular location: Secreted
Subcellular location (Human Protein Atlas): Vesicles
Pathways (Reactome):
Metabolism of proteins: Post-translational protein phosphorylation; Regulation of Insulin-like Growth Factor (IGF) transport and uptake by Insulin-like Growth Factor Binding Proteins (IGFBPs)
Gene Ontology:
Molecular function: protein binding; hormone activity
Biological process: signal transduction
Cellular component: extracellular region; endoplasmic reticulum lumen; secretory granule
Genetic constraint (gnomAD): Loss-of-function variants: 38 observed, 66.07 expected, observed/expected ratio (o/e) 0.58, 90% interval 0.44 to 0.75. The upper end of that interval is the gene's LOEUF score, 0.75, which puts it in group 3 of 6, group 1 being the genes least tolerant of losing a copy. Missense variants: 760 observed, 805.51 expected, observed/expected ratio (o/e) 0.94, 90% interval 0.89 to 1. Synonymous variants: 299 observed, 296.49 expected, observed/expected ratio (o/e) 1.01, 90% interval 0.92 to 1.11.
Homologues: Orthologues: chimpanzee CHGB (98% identical), macaque CHGB (93% identical), dog CHGB (73% identical), rabbit CHGB (68% identical), rat Chgb (65% identical), pig CHGB (64% identical), mouse Chgb (64% identical), guinea pig CHGB (61% identical), tropical clawed frog chgb (29% identical). Paralogues in human: CHGA (16% identical).
Diseases named in the same sentence as CHGB in open-access papers:
CHGB is named in the same sentence as 53 diseases in open-access papers, as found by Europe PMC text mining. Sharing a sentence is not in itself a finding about the gene and the disease. The quoted sentences say what the papers report.
schizophrenia (8 papers, 2009 to 2025). A major psychotic disorder characterized by abnormalities in the perception or expression of reality. "Chromogranin B (CHGB) is a member of the chromogranin gene family and has been identified as a potential biomarker related to the risk of schizophrenia." (PMID 37061663, 2023). "CHGB is known to be associated with neurodegenerative diseases, including schizophrenia and Parkinson's disease." (PMID 36582614, 2022). "Subsequent Japanese studies have reported significant associations between schizophrenia and the CHGB gene, which belongs to the same family as CHGA46." (PMID 28974776, 2017). "There are also positive human schizophrenia association studies with chromogranin B which is a closely related gene." (PMID 19370154, 2009). "Recently, a potential gene that may affect a person’s risk of developing schizophrenia is CHGB, and its variants on schizophrenia might possibly affect the levels of dopamine via interfering with neurotransmission pathway." (PMID 40636521, 2025). "Additionally, we found two missense mutations in chromogranin B (CHGB) that have been linked to Schizophrenia." (PMID 32121108, 2020). "Further studies are needed to clearly highlight the correlation between dopamine and the role of the CHGB gene in schizophrenia." (PMID 40636521, 2025). "Several neuropeptides were identified from schizophrenia patient-derived neurons, including chromogranin B (CHGB), neurotensin, and natriuretic peptide." (PMID 38302561, 2024). "Although it is known that the polymorphism results in reduced levels of chromogranin B,31 the relationship between chromogranin and tPA in schizophrenia has not been elucidated yet." (PMID 26731441, 2016).
Alzheimer disease (5 papers, 2005 to 2024). A progressive, neurodegenerative disease characterized by loss of function and death of nerve cells in several areas of the brain leading to loss of cognitive function such as memory and language. "There was a significant loss of chromogranin B – immunoreactivity in the dorsolateral, the entorhinal, and orbitofrontal cortex in Alzheimer's disease." (PMID 16321154, 2005). "Secretogranin-1, the protein encoded by CHGB, has been found in cerebrospinal fluid in patients with Alzheimer’s disease and these levels correlate with amyloid β and amyloid precursor protein levels in cerebrospinal fluid (CSF)." (PMID 39336788, 2024). "Chromogranin B – immunoreactive material was found in 15% of plaques in Alzheimer's disease." (PMID 16321154, 2005). "Furthermore, changes in CHGB neuropeptides in the SZ iNs are noteworthy because CHGB neuropeptide forms are dysregulated in human Alzheimer’s disease (AD) brains with severe cognitive deficits, and CHGB neuropeptides accumulate in amyloid plaques of human AD brains." (PMID 38302561, 2024).
glioma (4 papers, 2022 to 2026). A benign or malignant brain and spinal cord tumor that arises from glial cells (astrocytes, oligodendrocytes, ependymal cells). "Furthermore, the roles of the IGRPS genes NR2C1, SEMA4G, CFP, and CHGB in gliomas and other cancers are uncharacterized." (PMID 41596318, 2026). "However, CHGB was suggested to be an immune-related signature for low-grade glioma and head and neck squamous cell carcinoma." (PMID 35281839, 2022). "From these genes, 8 were identified as independent prognostic factors for glioma (FGFR1, FLT3, VTN, NR2C1, SEMA4G, CFP, S100P, CHGB)." (PMID 41596318, 2026). "The role of other genes (NR2C1, SEMA4G, CFP, CHGB) included in IGRPS has not been elucidated in gliomas and other tumors." (PMID 36676646, 2022).
neuroendocrine tumors (4 papers, 2017 to 2021). "Until 2003, a breast cancer could be classified as a primary neuroendocrine tumor when expressing chromogranin A, chromogranin B, or synaptophysin in more than 50% of the total cell population." (PMID 33584543, 2020). "In addition, in most neuroendocrine cells, Chromogranin B (CgB) coexists with CgA, and it can be used complementary with CgA as an important marker for detecting neuroendocrine tumors." (PMID 28540290, 2017).
Parkinson disease (4 papers, 2019 to 2025). A progressive degenerative disorder of the central nervous system characterized by loss of dopamine producing neurons in the substantia nigra and the presence of Lewy bodies in the substantia nigra and locus coeruleus. "We detect a significant decrease in two peptides for CHGB in Parkinson’s disease CSF." (PMID 31721001, 2019).
breast carcinoma (3 papers, 2020 to 2023). "To further understand the biology of NE breast tumors, we used Molecular Taxonomy of Breast Cancer International Consortium (METABRIC) database and isolated tumors which expressed neuroendocrine markers SCG2, CHGB, CHGA and SYP." (PMID 37071013, 2023). "Surprisingly, we also observed the unexpected appearance of ramifications reminiscent of neuroendocrine cells and an increased expression of neuroendocrine markers SCG2 and CHGB in these cells, indicating that SASP is able to induce NED in breast cancer epithelial cells." (PMID 37071013, 2023). "Lower expression of CHGB was reported in invasive ductal carcinoma of the breast as compared to non-invasive ductal carcinoma; and breast cancer patients with CHGB negative tumors have poorer prognosis than those with CHGB positive tumors." (PMID 34797887, 2021).
colon cancer (3 papers, 2019 to 2022). "Two immune related genes (CHGB and SCT) were identified to be correlated with colon cancer survival (HR = 1.39, P = 0.01; HR = 1.26, P = 0.02, respectively)." (PMID 33664769, 2021). "In the univariate Cox analysis, two genes (CHGB and SCT) were shown to be correlated with the survival of patients with colon cancer, while only SCT was found to be an independent prognostic factor based on the multivariate analysis (P < 0.001)." (PMID 33664769, 2021).
neuroblastoma (3 papers, 2021 to 2024). Neuroblastoma (NB) is the most common solid, extracranial childhood tumor. "Amongst these genes were neuroblastoma-associated genes NTRK1, BCL11A, TH and CHGB, as well as HMX1, a transcription factor on chromosome 4 that is a master regulator of neural crest development." (PMID 36071103, 2022). "Significant expression of (nor-)adrenergic (“NOR”) markers (i.e., CHGA, CHGB, DBH, TH, PHOX2A, and PHOX2B) is common for healthy sympatho-adrenal cells and tumor NOR populations identified in low-risk neuroblastoma cases (FDR < 0.01, Welch’s t-test)." (PMID 34493726, 2021).
pancreatic neuroendocrine tumor (3 papers, 2021 to 2025). Pancreatic endocrine tumor, also known as pancreatic neuroendocrine tumor (PNET), describes a group of endocrine tumors originating in the pancreas that are usually indolent and benign, but may have the potential to be malignant. "The most down-regulated gene from the meta-analysis was chromogranin-B (CHGB), which is associated with malignancy and metastasis in pancreatic neuroendocrine tumors (PNETs)." (PMID 34797887, 2021). "Furthermore, although only a small percentage of patients with pancreatic neuroendocrine tumors exhibit elevated serum levels of pancreastatin and CHGB, ranging from 17 to 57%, their clinical significance remains uncertain." (PMID 41034734, 2025).
pheochromocytoma (3 papers, 2021 to 2022). "CHGB was first identified in pheochromocytoma and encodes proteins that are mainly expressed in endocrine cells and neurons." (PMID 35935970, 2022). "CHGB is initially identified in pheochromocytoma, and it encodes a tyrosinesulfated secretory protein (CHGB protein) that is expressed in endocrine cells and neurons." (PMID 33390791, 2021). "Specificity, sensitivity, positive and negative predictive value of apelin, SDHB and CHGB in differentiating metastatic from non-metastatic pheochromocytoma and paraganglioma." (PMID 35574028, 2022).
small cell lung carcinoma (3 papers, 2016 to 2023). Small cell lung cancer (SCLC) is a highly aggressive malignant neoplasm, accounting for 10-15% of lung cancer cases, characterized byrapid growth, and early metastasis. "Similar to the neuroendocrine subtype of small cell lung cancers, these tumors also displayed upregulation of the neuroendocrine markers chromogranin A and chromogranin B, leading us to name this cluster the neuroendocrine subtype." (PMID 26776158, 2016).
cognitive deficits (2 papers, 2022 to 2024). "Multiple sevoflurane exposures can cause brain damage and cognitive deficits in newborn mice, mediated via elevated levels of CHGB, PTEN, and MAP2c protein expression and reduced SOD2 expression." (PMID 36582614, 2022).
diabetes (2 papers, 2021 to 2023). "We also found increases in the diabetes-associated Islet-cell autoantigen PTPRN, a 60-kDa type 1 membrane protein associated with the pancreatic and adrenal DCSVs together with Chromogranin B, a master regulator of DCSV biogenesis and function." (PMID 33711921, 2021). "In addition, CHGA, CHGB, SCG2, and some CHGA cleavage products affect glucose homeostasis and different types of diabetes." (PMID 37249284, 2023).
Hypertension (2 papers, 2021 to 2024). The presence of chronic increased pressure in the systemic arterial system. "CHGB encodes chromogranin B, a key protein in the process of catalyzing the formation of catecholamine storage vesicles and regulating sympathetic activity, and thus becomes one of the potentially pathogenic genes related to hypertension." (PMID 38977948, 2024). "Secretogranin-1 (CHGB) presents in the secretory granules in atrial myoendocrine cells and is co-localized with atrial natriuretic peptide (ANP) while CHGB genetic variation results in oxidative stress and hypertension." (PMID 33509101, 2021).
leprosy (2 papers, 2017 to 2020). Leprosy is a chronic infectious disease affecting primarily the skin and peripheral nervous system. "In conclusion, the GAL3ST4 and the CHGB allele variants 23 and 48 are novel genetic loci involved in susceptibility to leprosy among female and male population, respectively." (PMID 29180661, 2017). "The CHGB gene may play an important role for leprosy susceptibility, and men with GG homozygous are less likely to suffer from leprosy." (PMID 29180661, 2017). "Overall, our study demonstrates a significant association of GAL3ST4 and CHGB polymorphisms with leprosy and suggests that these gene polymorphisms may be a contributing factor in leprosy susceptibility." (PMID 29180661, 2017). "Subsequently, 231,176 SNPs were originally obtained and several novel common variants (MAF≥5% in the 1,000 Genomes Project data) were recognized including two novel mutations (rs16991480 and rs76791154) in CHGB, but no rare risk variants significantly associated with leprosy were identified." (PMID 33362202, 2020). "Additionally, our genetic findings combined with the expression of GAL3ST4 and CHGB in PBMC, point strongly to an important function of secretogranin and galactose-3-O-sulfotransferase involved in the synthesis and metabolism of glycoprotein in the study of leprosy pathogenesis." (PMID 29180661, 2017).
pancreatic cancer (2 papers, 2020 to 2022). "SCG5, CRYBA2, CPE and CHGB genes are associated with the prognosis of pancreatic cancer, and their low expression suggests a poor prognosis." (PMID 33164330, 2020). "Prognostic analysis showed the expression levels of four genes were significantly correlated with the overall survival time of patients with pancreatic cancer, namely SCG5, CRYBA2, CPE and CHGB." (PMID 33164330, 2020).
acne (1 paper, 2024). An inflammatory process of the sebaceous glands which is characterized by comedones, nodules, papules and/or pustules on the skin. "While dermcidin, granulysin (GNLY), RANTES (CCL5), perforin, CXCL9, and two neuropeptides (substance P and chromogranin B) remained unaffected either in untreated acne patients as well as by isotretinoin treatment." (PMID 39744637, 2024). "However, the overexpression of substance P and chromogranin B is not universally recognized in acne skin." (PMID 39744637, 2024).
adenoma (1 paper, 2025). A neoplasm arising from the epithelium. "Focusing on the promoter methylation status of the neuroendocrine markers chromogranin A (CgA), chromogranin B (CgB) and CD56 (NCAM1) confirmed congruently lower methylation levels in NETs and PitNETs/adenomas compared to adenomas." (PMID 41060331, 2025).
amyotrophic lateral sclerosis (1 paper, 2024). Amyotrophic lateral sclerosis (ALS) is a neurodegenerative disease characterized by progressive muscular paralysis reflecting degeneration of motor neurons in the primary motor cortex, corticospinal tracts, brainstem and spinal cord. "Patient 12, a 49 years old female, presents compound mutations in chromogranin B4 (CHGB), potentially associated with amyotrophic lateral sclerosis early onset." (PMID 38418480, 2024). "However, one variant in the CHGB gene (rs742710, AF = 1.07E−01), present in patient 12, has been previously reported to be potentially causative for amyotrophic lateral sclerosis early onset." (PMID 38418480, 2024).
Creutzfeldt-Jakob disease (1 paper, 2005). "Chromogranin B – immunoreactive material was selectively associated with prion protein deposits in Creutzfeldt-Jakob disease." (PMID 16321154, 2005).
Crohn disease (1 paper, 2022). A gastrointestinal disorder characterized by chronic inflammation involving all layers of the intestinal wall, noncaseating granulomas affecting the intestinal wall and regional lymph nodes, and transmural fibrosis. "Previous studies have found increased fecal CHGB in patients with UC in remission, and patients with UC show higher serum levels of CHGB than patients with Crohn’s disease." (PMID 35465329, 2022).
insulinoma (1 paper, 2018). "The LC/MS data obtained from the two glucagonoma cases (Case 1 pre‐ and post‐treatment, and Case 2), an insulinoma (Case 3) and 62 control samples from healthy individuals were interrogated for glucagon, CHGA, CHGB, SCG2, insulin, c‐peptide, and the internal standard bovine insulin." (PMID 29857350, 2018).
lung carcinoma (1 paper, 2015). "Of these 64 mRNAs, 38 mRNAs were down-regulated in lung cancer patients, of which the top 5 mRNAs were CHGB, B4GALT1, ZNF434, GLB1, and ASCL1 (p≤0.0001)." (PMID 25705890, 2015).
lymph node metastasis (1 paper, 2021). "Previous research demonstrated that CHGB promoted the occurrence and advanced lymph node metastasis of nasopharyngeal carcinoma." (PMID 34220923, 2021).
Lymphatic Metastasis (1 paper, 2025). Transfer of a neoplasm from its primary site to lymph nodes or to distant parts of the body by way of the lymphatic system. "Only 6 genes, namely CHGA, CHGB, PCSK2, PCSK1N, DLGAP1 and DLGAP3 were down-Regulated in the lymphatic metastasis group." (PMID 41431044, 2025).
meningioma (1 paper, 2026). A generally slow growing tumor attached to the dura mater. "NSE, CD56, and chromogranin B were detected in 91%, 44%, and 16% of meningiomas, respectively." (PMID 41769706, 2026). "We aimed to explore neuroendocrine differentiation in meningiomas by investigating the following neuroendocrine markers: neural cell adhesion molecule (CD56/NCAM), chromogranin A, chromogranin B, chromogranin C, neuron-specific enolase (NSE), secretagogin, and synaptophysin." (PMID 41769706, 2026).
Merkel cell carcinomas (1 paper, 2004). "Merkel cell carcinomas also label for neuron specific enolase (virtually all), chromogranin B (100%), chromogranin A (72%), secretoneurin (22%), and synaptophysin (39%)." (PMID 15550173, 2004).
metastatic disease (1 paper, 2019). "In a recent study, low expression of Chromogranin B (CHGB) (mRNA and protein) was associated with both PASS scores, occurrence of metastatic disease and shorter disease-related survival, suggesting CHGB as a possible marker for pinpointing PPGL with high PASS scores and aggressive tumor behavior." (PMID 30769931, 2019).
rectal cancer (1 paper, 2023). A primary or metastatic malignant neoplasm that affects the rectum. "Interestingly, this miRNA regulates unique genes from all three anatomical locations, including CHGB in the right colon, CACNA1B and GLRA3 in the left colon, and TFAP2B in rectal cancer." (PMID 37987361, 2023).
sporadic amyotrophic lateral sclerosis (1 paper, 2024). Sporadic amyotrophic lateral sclerosis is a amyotrophic lateral sclerosis in which there is no known cause, such as no family history. "This study investigated the role of the CHGB P413L variant (rs742710) in sporadic amyotrophic lateral sclerosis (sALS) within the Bulgarian population." (PMID 39336788, 2024).
thymoma (1 paper, 2021). A neoplasm arising from the epithelial cells of the thymus. "Relative to the 6 normal thymuses and 2 thymomas, the 11 thymic NETs had significantly higher mRNA for neuroendocrine markers (more than 100-fold, P < 0.02) chromogranin A, chromogranin B, neuron-specific enolase, and synaptophysin, confirming the neuroendocrine origin." (PMID 34515662, 2021). "Curiously, the thymoma with neuroendocrine differentiation had high chromogranin B but without significant expression of other neuroendocrine markers." (PMID 34515662, 2021).